NAP1L1 (nucleosome assembly protein 1 like 1)
Description:
Histone chaperone that plays a role in the nuclear import of H2A-H2B and nucleosome assembly. Also participates in several important DNA repair mechanisms: greatly enhances ERCC6-mediated chromatin remodeling which is essential for transcription-coupled nucleotide excision DNA repair. Also stimulates homologous recombination (HR) by RAD51 and RAD54 which is essential in mitotic DNA double strand break (DSB) repair. Plays a key role in the regulation of embryonic neurogenesis (By similarity). Promotes the proliferation of neural progenitors and inhibits neuronal differentiation during cortical development (By similarity). Regulates neurogenesis via the modulation of RASSF10; regulates RASSF10 expression by promoting SETD1A-mediated H3K4 methylation at the RASSF10 promoter (By similarity). (Microbial infection) Positively regulates Epstein-Barr virus reactivation in epithelial cells through the induction of viral BZLF1 expression. (Microbial infection) Together with human herpesvirus 8 protein LANA1, assists the proper assembly of the nucleosome on the replicated viral DNA.
Synonyms: NRP; NAP1; NAP1L; MGC8688; MGC23410
Tractability: PROTAC: ubiquitination databases record sites on it; its protein half-life has been measured.
Gene: Protein-coding gene on chromosome 12 (76,032,987 to 76,085,261, reverse strand). Ensembl gene ENSG00000187109.
Subcellular location: Nucleus; Chromosome; Melanosome; Cytoplasm
Subcellular location (Human Protein Atlas): Microtubules
Gene Ontology:
Molecular function: histone chaperone activity; protein binding; RNA binding
Biological process: DNA replication; nucleosome assembly; positive regulation of cell population proliferation; positive regulation of neural precursor cell proliferation; positive regulation of neurogenesis
Cellular component: cytoplasm; membrane; nucleus; chromatin; chromosome; melanosome
Genetic constraint (gnomAD): Loss-of-function variants: 6 observed, 43.39 expected, observed/expected ratio (o/e) 0.14, 90% interval 0.075 to 0.27. The upper end of that interval is the gene's LOEUF score, 0.27, which puts it in group 1 of 6, group 1 being the genes least tolerant of losing a copy. Missense variants: 233 observed, 373.2 expected, observed/expected ratio (o/e) 0.62, 90% interval 0.56 to 0.7. Synonymous variants: 103 observed, 116.44 expected, observed/expected ratio (o/e) 0.88, 90% interval 0.75 to 1.04.
Homologues: Orthologues: pig NAP1L1 (99% identical), mouse Nap1l1 (98% identical), rat Nap1l1 (98% identical), guinea pig NAP1L1 (97% identical), rabbit NAP1L1 (97% identical), dog NAP1L1 (91% identical), chimpanzee NAP1L1 (90% identical), tropical clawed frog nap1l1 (88% identical), zebrafish nap1l1 (82% identical). Paralogues in human: NAP1L4 (64% identical), NAP1L2 (48% identical), NAP1L3 (41% identical), SET (24% identical), SETSIP (24% identical), TSPYL2 (20% identical), TSPYL4 (19% identical), TSPYL1 (18% identical), NAP1L5 (15% identical), TSPYL5 (15% identical), TSPYL6 (15% identical), TSPY1 (13% identical), and 6 more.
Diseases named in the same sentence as NAP1L1 in open-access papers:
NAP1L1 is named in the same sentence as 57 diseases in open-access papers, as found by Europe PMC text mining. Sharing a sentence is not in itself a finding about the gene and the disease. The quoted sentences say what the papers report.
hepatocellular carcinoma (13 papers, 2019 to 2025). A malignant tumor that arises from hepatocytes. "NAP1L1 is a prognostic biomarker and contributes to doxorubicin chemotherapy resistance in human hepatocellular carcinoma." (PMID 36980210, 2023). "LncRNA CDKN2B-AS1 promotes proliferation and metastasis of human hepatocellular carcinoma through the let-7c-5p/NAP1L1 axis." (PMID 36374212, 2022). "In the meantime, a study has manifested the augment of NAP1L1 in hepatocellular carcinoma (HCC) with motivation of the growth and metastasis of cells." (PMID 34898380, 2022). "NAP1L1 has been reported to be highly expressed in several types of human malignancies, including colorectal cancer, hepatocellular cancer, lung adenocarcinoma, and renal cancer; however, its expression level in OC is not yet clear." (PMID 35351053, 2022). "A recent paper has also demonstrated that NAP1L1 is a prognostic biomarker and contributes to doxorubicin chemotherapy resistance in hepatocellular carcinoma." (PMID 32850460, 2020). "Importantly, NAP1L1 also inhibits the sensitivity of hepatoma cells to doxorubicin through its effect on CSCs." (PMID 36980210, 2023). "In previous studies, NAP1L1 has been shown to promote tumor cell proliferation in various human malignancies, including colorectal cancer, hepatocellular cancer, lung adenocarcinoma, renal cancer, and neuroendocrine neoplasms, and overexpression of NAP1L1 is related to a poor prognosis." (PMID 35351053, 2022). "Our findings support that NAP1L1 is a prognostic biomarker and may contribute to chemotherapy resistance in human hepatocellular carcinoma." (PMID 31516385, 2019). "We have previously shown that nucleosome assembly protein 1-like 1 (NAP1L1) plays an important role in the abnormal proliferation of hepatocellular carcinoma (HCC) cells." (PMID 38538582, 2024). "NAP1L1 has been reported to be significantly involved in the carcinogenesis of hepatocellular carcinoma (HCC)." (PMID 34368121, 2021).
pancreatic neuroendocrine neoplasm (8 papers, 2014 to 2024). A neoplasm with neuroendocrine differentiation that arises from the pancreas. "A number of studies have reported NAP1L1 is upregulated and has a carcinogenic function in various tumors such as breast cancer, pancreatic neuroendocrine neoplasm, colon cancer and so on." (PMID 38816735, 2024). "In pancreatic neuroendocrine neoplasms, NAP1L1 has been proved to be involved in promotion of tumor cell proliferation and regulation of cell entry into the S phase." (PMID 35351053, 2022). "In pancreatic neuroendocrine neoplasms, NAP1L1 promotes tumor cell proliferation and regulates cell entry into the S phase via inhibition of the mTOR pathway." (PMID 35351053, 2022). "In colorectal cancer and pancreatic neuroendocrine neoplasm, NAP1L1 was found to be a biomarker, involved in the pathogenesis of these two types of cancers." (PMID 34368121, 2021). "NAP1L1 has been shown as a potential tumor promoter and participates in the pathogenesis of several tumors including colorectal cancer, renal cancer, and pancreatic neuroendocrine neoplasm." (PMID 34368121, 2021). "Our data identifies that NAP1L1 epigenetically promotes tumor cell proliferation in pancreatic neuroendocrine neoplasms through inhibition of the mTOR pathway and the tumor suppressor p57Kip2; the principal mechanism is via p57Kip2 promoter methylation." (PMID 25071868, 2014). "NAP1L1 is over-expressed in pancreatic neuroendocrine neoplasm metastases and epigenetically promotes cell proliferation through regulation of p57Kip2 promoter methylation." (PMID 25071868, 2014). "The high expression of NAP1L1 has existed in the heap of human neoplasms covering nasopharyngeal carcinoma, lung adenocarcinoma, glioblastoma, colon cancer, colorectal cancer, breast cancer, small-intestinal carcinoid, and pancreatic neuroendocrine neoplasm." (PMID 35664324, 2022). "In previous studies, NAP1L1 expression was reported to be upregulated in several cancers such as renal cancer cell, pancreatic neuroendocrine neoplasm and colon cancer, but its prognostic value has not yet been reported." (PMID 31516385, 2019).
colorectal cancer (7 papers, 2020 to 2025). A primary or metastatic malignant neoplasm that affects the colon or rectum. "NAP1L1 overexpression has been associated with a poor prognostic outcome and has previously been found to promote cellular proliferation in various neoplastic conditions including colorectal cancer, HCC, lung adenocarcinoma, and neuroendocrine cancers." (PMID 40176914, 2025).
colon cancer (6 papers, 2008 to 2024). "Clinical research also showed that NAP1L1 was upregulated in colon cancer patients' serum and was a novel predictive and prognostic biomarker for colon cancer and lung adenocarcinoma." (PMID 37593048, 2023). "NAP1L1 is upregulated in small-intestinal neuroendocrine cell-derived neoplastic tissues, colon cancer, and malignant adenocarcinoma as compared to normal mucosa." (PMID 34959221, 2021). "NAP1l1 has been shown to be a tumor marker for colon cancer." (PMID 18535662, 2008).
glioma (6 papers, 2017 to 2025). A benign or malignant brain and spinal cord tumor that arises from glial cells (astrocytes, oligodendrocytes, ependymal cells). "In our previous study, NAP1L1 was found to be significantly upregulated in glioma as compared to the para-tumor tissues and high NAP1L1 expression was associated with poor survival in patients with glioma." (PMID 34959221, 2021). "But the comprehensive molecular mechanisms of NAP1L1 underlying glioma onset and progression remain unclear." (PMID 34959221, 2021). "Our findings implicated NAP1L1 as a potential diagnostic biomarker and therapy target for glioma." (PMID 34959221, 2021). "Furthermore, OS and DFS analyses illustrated that NAP1L1 overexpression was an unfavorable factor associated with reduced survival time of glioma patients." (PMID 34959221, 2021). "Nevertheless, the biological role as well as the molecular mechanism of NAP1L1 underlying glioma onset and progression remains unknown." (PMID 34959221, 2021). "In glioma and ovarian cancers, NAP1L1, via its interaction with HDGF, activated c-Jun, an oncogenic transcription factor, to induce CCND1/CDK4/CDK6 expression resulting in cellular proliferation and chemoresistance to cisplatin." (PMID 40176914, 2025). "For example, MYH9 is involved in glioma proliferation and drug resistance through the regulation of NAP1L1 deubiquitination." (PMID 39550407, 2024). "A previous study conducted by our group revealed that NAP1L1 enhances glioma progression by activating the c-Jun signaling pathway." (PMID 37770914, 2023). "The immunofluorescence assay demonstrated that MYH9 and NAP1L1 mainly colocalized in the glioma cell cytoplasm." (PMID 37770914, 2023). "Altogether, our results show that MYH9 plays a role in glioma progression by regulating NAP1L1 deubiquitination." (PMID 37770914, 2023). "The immunofluorescence assay demonstrated that NAP1L1 and c-Myc mainly colocalized in the glioma cell cytoplasm, with minor nuclear distribution." (PMID 37770914, 2023). "Subsequently, we performed an endogenous Co-IP assay, which showed that NAP1L1 interacted with c-Myc in glioma cells." (PMID 37770914, 2023). "Altogether, these results demonstrated that c-Myc regulated by NAP1L1 promoted glioma cell proliferation by inducing CCND1/CDK4." (PMID 37770914, 2023). "A previous study conducted by our group revealed that NAP1L1 enhanced glioma progression by activating the c-Jun signaling pathway." (PMID 37770914, 2023). "The results of this assay demonstrated that MYH9 greatly decreased the ubiquitination level of NAP1L1 in glioma cells." (PMID 37770914, 2023). "Immunofluorescence assay results demonstrated that NAP1L1 and c-Myc mainly colocalized in the glioma cell cytoplasm, with minor nuclear distribution." (PMID 37770914, 2023). "The CCK8 assay results showed that NAP1L1 overexpression enhanced cell proliferation in MYH9-silenced glioma cells." (PMID 37770914, 2023). "Subsequently, the endogenous Co-IP assay indicated that NAP1L1 interacted with c-Myc in glioma cells." (PMID 37770914, 2023). "An endogenous co-IP assay was performed to indicate that MYH9 interacted with NAP1L1 in glioma cells." (PMID 37770914, 2023). "The survival analysis demonstrated that overexpression of NAP1L1 was an adverse factor that decreased the survival duration of glioma patients." (PMID 34959221, 2021). "The findings showed that NAP1L1 knockdown significantly inhibited the proliferation of glioma cells in comparison with that in the control group." (PMID 34959221, 2021). "We found that NAP1L1 knockdown, that is, in mice that carried the shNAP1L1 glioma cells, resulted in the formation of smaller tumors as compared to those in the control (sh-NC) group." (PMID 34959221, 2021). "Glioma patients having high expression of both NAP1L1 and HDGF showed the worst survival prognoses as compared to other groups." (PMID 34959221, 2021).
glioma (continued). "In this study, we aimed to investigate the molecular functions of NAP1L1 in glioma and its involvement in cisplatin chemoresistance, if any." (PMID 34959221, 2021). "A tissue microarray (TMA) containing 108 glioma and 24 para-tumor tissue samples was used to assess the NAP1L1 expression level." (PMID 34959221, 2021). "Next, we investigated the effect of attenuated expression of NAP1L1 on the growth of glioma cells in vitro." (PMID 34959221, 2021). "The RT-qPCR analysis also confirmed that the mRNA level of NAP1L1 was dramatically upregulated in 24 gliomas tissues as compared to the corresponding 24 para-tumor tissues." (PMID 34959221, 2021). "The RT-qPCR analysis also confirmed that NAP1L1 mRNA expression was significantly enhanced in 24 gliomas tissues as compared to the 24 corresponding para-tumor tissues (P < 0.001)." (PMID 34959221, 2021). "Next, we found that downregulated NAP1L1 attenuated the proliferative ability of glioma cells in vivo and in vitro." (PMID 34959221, 2021). "High expression of NAP1L1 in glioma tissues was significantly related to WHO grades I~IV, KPS <80, Ki-67 index ≥20%, and recurrence." (PMID 34959221, 2021). "A tissue microarray (TMA) with 108 glioma tissue samples and 24 para-tumor tissues was used to assess the expression level of NAP1L1." (PMID 34959221, 2021). "The correlation of NAP1L1 or HDGF protein expression with clinicopathological parameters in gliomas." (PMID 34959221, 2021). "Immunohistochemical (IHC) staining for the expressions of NAP1L1 and HDGF showed that NAP1L1 positive signals were mostly localized to the cytoplasm of glioma cells, while those of HDGF was mainly in the cytoplasm and nuclei." (PMID 34959221, 2021). "Moreover, the immunofluorescence assay revealed that MYH9 and NAP1L1 were primarily present in the cytoplasm of glioma cells." (PMID 37770914, 2023). "Together, these findings suggest that MYH9 affects glioma progression by interacting with NAP1L1." (PMID 37770914, 2023). "Since proteins can be degraded via the ubiquitin‒proteasome pathway, we attempted to determine whether MYH9 regulates NAP1L1 degradation by inhibiting its ubiquitination in glioma cells." (PMID 37770914, 2023). "To explore in more detail whether NAP1L1 participates in the promotion of MYH9 in glioma, we transfected MYH9-silenced glioma cells with an NAP1L1 plasmid." (PMID 37770914, 2023). "In addition, NAP1L1 was found to affect MYH9-mediated regulation of the c-Myc pathway in glioma cells." (PMID 37770914, 2023). "The endogenous Co-IP assay showed that MYH9 interacted with NAP1L1 in glioma cells." (PMID 37770914, 2023). "In addition, we investigated the protein levels of genes associated with cell cycle and apoptosis in the U251 and U87 glioma cells with stable suppression of NAP1L1." (PMID 34959221, 2021). "The findings demonstrated that NAP1L1 interacted with HDGF in glioma." (PMID 34959221, 2021). "NAP1L1 is an oncogene, and its knockdown inhibits glioma cell proliferation." (PMID 34959221, 2021). "Interestingly, glioma cells with stably silenced NAP1L1 showed significantly enhanced sensitivity to cisplatin (DDP) treatment." (PMID 34959221, 2021). "Moreover, NAP1L1 expression was positively correlated with the expression of HDGF in glioma tissues." (PMID 34959221, 2021). "The data demonstrated that at the mRNA level, the expression of NAP1L1 was elevated in glioma." (PMID 34959221, 2021). "Our results indicated that NAP1L1 may be a tumor promoter that could participate in glioma pathogenesis." (PMID 34959221, 2021). "High expression of NAP1L1 was positively correlated with WHO grade, KPS, Ki-67 index, and recurrence, which indicated that NAP1L1 could promote glioma progression." (PMID 34959221, 2021). "Furthermore, reducing the level of NAP1L1 enhanced the sensitivity to cDDP chemotherapy in glioma cells." (PMID 34959221, 2021). "Moreover, NAP1L1 expression was also positively correlated with the HDGF expression in glioma tissues." (PMID 34959221, 2021).